LGALS1 (galectin 1)
Diseases named in the same sentence as LGALS1 in open-access papers (continued):
Sharing a sentence is not in itself a finding about the gene and the disease.
pancreatic cancer (continued). "Additionally, activated PSCs play a vital role in the pancreatic cancer microenvironment by secreting molecules such as TGFβ, IL-6, stromal cell-derived factor-1 (SDF-1), hepatocyte growth factor (HGF) and galectin-1 to promote pancreatic cancer progression." (PMID 30060755, 2018). "However, few studies have elucidated the precise role of Galectin-1 in the pancreatic cancer-stroma interaction." (PMID 29156810, 2017). "Our previous study indicated that the cytokine TGF-β1 could upregulate Galectin-1 expression in PSCs to further promote the proliferation and invasion of pancreatic cancer cells, and support tumor establishment and growth." (PMID 29156810, 2017). "So the Galectin-1 in the activated PSCs of stromal may be has an important role on the development of pancreatic cancer." (PMID 24595374, 2014). "To determine whether the PSCs derived Galectin-1 induced the proliferative activity of pancreatic cancer cells, we analyzed the S-phase fraction (SPF) of CFPAC-1 by flow cytometry, and the percentages of cells in Apoptosis, G1, S, and G2 were quantified." (PMID 24595374, 2014). "However, the molecular mechanisms by which Galectin-1 promotes the malignant behavior of pancreatic cancer cells remain unclear." (PMID 29156810, 2017). "Tumor-derived galectin-1 (Gal-1) induces tumor angiogenesis and promotion of immunosuppression by T cell apoptosis in several types of cancers, including melanomas, NB, lung cancers, and pancreatic carcinomas, therefore correlating with tumor aggressiveness and metastasis." (PMID 27686492, 2016). "Galectin-1 staining intensity of pancreatic cancer tissue was associated with increase in tumor size, lymph node metastasis, perineural invasion and differentiation and UICC stage, and served as the independent prognostic indicator of poor survival of pancreatic cancer." (PMID 24595374, 2014). "In addition, the in vivo and vitro experiments also verified the PSCs derived Galectin-1 might increase the reproductive activity and invasion ability of pancreatic cancer cells, and facilitate the growth of the subcutaneous xenografts." (PMID 24595374, 2014). "Depending on the counter-receptor and its glycosylation, galectin-1 can differentially affect a variety of cellular functions, including cell proliferation, adhesion and migration, apoptosis in activated T lymphocytes, and induction of anoikis in pancreatic carcinoma cells." (PMID 19898636, 2009). "Inhibitors: lab trials have spotlighted a Galectin-1 inhibitor, LLS2, that augmented the efficacy of chemotherapy agent paclitaxel across multiple human cancer cell lines, encompassing pancreatic cancer cells." (PMID 37958483, 2023). "Analyzed IHC biomarkers that can differentiate pancreatic cancer from chronic pancreatitis encompass REG4, POSTN, CA242, Galectin-1, maspin, pVHL, IMP3, CD13, and PAM4." (PMID 34988027, 2021). "The most specific IHC biomarkers consist of Galectin-1, Maspin, KOC, and S100P, whereas MUC1 is the least specific IHC biomarker for the diagnosis of pancreatic cancer in the current review." (PMID 34988027, 2021). "Among our protein pool, we found Galectin-1 (LGALS1), a glycan-binding protein that is highly expressed in PDAC stroma, and a significant contributor to pancreatic cancer progression." (PMID 32197468, 2020). "Our meta-analysis supported the various function of different galectin subtypes in cancer prognosis, that converse to galectin-1, high levels of galectin-4 or galectin-9 predicted better OS and DFS in pancreatic cancer." (PMID 31832021, 2019). "Moreover, activated PSCs-secreted galectin-1 promotes the apoptosis of CD3+CD4+ and CD3+CD8+ effector T cells, developing a PSC-dependent immunoprivilege in the pancreatic cancer microenvironment." (PMID 35719926, 2022).
pancreatic cancer (continued). "Furthermore, Chen and colleagues found that PRELP, LGALS1 and RPS8 might be significant prognostic factors for pancreatic cancer, while another study showed that PNMA1 was associated with prolonged overall survival and might serve as a prognostic biomarker for pancreatic cancer." (PMID 29515771, 2018). "Galectin-1, which has been discussed previously, is expressed by PSCs and can induce PSC secretion of SDF-1 by NF-κB signaling and increase the migration and invasion of pancreatic cancer cells." (PMID 30060755, 2018). "Furthermore, PSCs derived Galectin-1 promotes the proliferative activity, MMP2 and MMP9 expression and invasion of pancreatic cancer cells in vitro, and tumor establishment and growth in vivo." (PMID 24595374, 2014). "To determine the effect of PSCs derived Galectin-1 on the progression of PDAC, we isolated human cancer PSCs (hCaPSC) and normal PSCs (hNPSC) from the resected pancreatic cancer tissue and the normal pancreas tissue of the patient undergoing operation for bile duct cancer respectively." (PMID 24595374, 2014). "In vitro and in vivo experiments indicated that TGF-β1 upregulated Galectin-1 expression in PSCs, which could further promotes the proliferative activity, MMP2 and MMP9 expression, and invasion of pancreatic cancer cells, as well as the tumor establishment and growth." (PMID 24595374, 2014). "Indeed, as Galectin-1 was recently reported to trigger EMT and tumor progression in human hepatocellular carcinoma, gastric cancer, and colon cancer, we hypothesized that it may also induce EMT in pancreatic cancer, which is the foundation of this research." (PMID 29156810, 2017).
glioblastoma (30 papers, 2009 to 2025). The most malignant astrocytic tumor (WHO grade IV). "LGALS1, for instance, has been implicated in several hallmark features of glioblastoma pathogenesis, including resistance to chemoradiotherapy, induction of neo-angiogenesis, and suppression of anti-tumour immune responses." (PMID 41516291, 2025). "High Galectin-1 expression has been associated with poor prognosis in various cancers, including ovarian cancer, glioblastoma, renal cell cancer, head and neck squamous cell carcinoma, and non–small-cell lung cancer." (PMID 37433225, 2023). "Increased LGALS1 expression in cancer cells such as lung, liver, ovarian, glioblastoma, and lymphoma has been associated with drug resistance (temozolomide, sorafenib, rituximab, and cisplatin)." (PMID 32197468, 2020). "In addition to delivering low-molecular-weight chemotherapy drugs, NPs can also be effective carriers of other molecules that inhibit tumor cell growth and survival––ribosome-inactivating proteins and small interfering RNAs that aim to knock out the gene encoding galectin-1 in glioblastoma cells." (PMID 40574222, 2025). "For example, the results from one study suggested that galectin-8 (along with galectin-1 and -3) may be associated with the tumor astrocyte invasion of the brain parenchyma, where it was shown that these galectins stimulated glioblastoma cell migration in vitro." (PMID 39337581, 2024). "Galectin-1, for instance, enhances glioblastoma cell migration via re-organisation of the actin cytoskeleton and upregulation of small GTPase RhoA expression." (PMID 41516291, 2025). "This study provides a comprehensive, family-wide analysis of galectins in glioblastoma, revealing that LGALS1, LGALS3, and LGALS9 are consistently overexpressed and strongly associated with adverse survival, immune dysregulation, and tumour-promoting pathways." (PMID 41516291, 2025). "Further, zebrafish models have been utilized to study the role of galectin-1 (LGALS1) in glioblastoma." (PMID 40710421, 2025). "Within this family, LGALS1, LGALS3, and LGALS9 have been most consistently implicated in glioblastoma progression, through roles in tumour proliferation, immune evasion, and resistance to therapy." (PMID 41516291, 2025). "LGALS1 acts as the immune heterogeneity and immunosuppression in plenty of cancer, such as glioblastoma, clear cell renal carcinoma, non-small cell lung cancer." (PMID 38965225, 2024). "Galectin 1 is highly expressed in glioblastoma stem cells and is important for immunomodulation and angiogenesis." (PMID 38012322, 2023). "Further, glioblastoma cells with defects in the Galectin-1 gene LGALS1 can decrease the percentage of M2 macrophages in the microenvironment." (PMID 36591221, 2022). "Galectin-1 knockdown also reduces macrophage polarization shift from M1 to M2 during glioblastoma progression in mice." (PMID 35692780, 2022). "We show by immunohistochemistry analysis of 122 glioblastoma biopsies that galectin-1 protein levels vary between tumours, with levels in recurrent glioblastoma higher than those in primary tumours or normal tissues." (PMID 35632759, 2022). "For instance, galectin-1 knockdown synergizes with dendritic cell vaccination and PD-1 blockade in glioblastoma." (PMID 34572756, 2021). "The aim of current study is to determine the prognostic significance of the galectin-1 expression level in patients with glioblastoma multiforme (GBM) undergoing adjuvant radiotherapy (RT)." (PMID 29378529, 2018). "Paraffin sections of our patient-derived glioblastoma xenografts (15 of 22 lines) were stained for galectin-1 expression." (PMID 22583806, 2012). "Previous studies, along with the current one, have proven galectin-1 to be important in the migration and invasion of glioblastoma cells, in GBM neoangiogenesis, and also, potentially, in GBM immune privilege." (PMID 22583806, 2012).
glioblastoma (continued). "This study illustrates a novel microarray data filtering algorithm that identified galectin-1 as a gene preferentially expressed at the glioblastoma-brain interface." (PMID 22583806, 2012). "We thus took advantage of our own patient-derived glioblastoma xenograft model in order to further decipher the roles of galectin-1 on GBM cell migration features." (PMID 22583806, 2012). "Galectin-1 was identified in this manner, and has proven in vitro and in vivo to be important in the migration and invasion of glioblastoma cells." (PMID 22583806, 2012). "Stable inhibition of galectin-1 expression in a glioblastoma cell line diminished the expression of several genes that either directly or indirectly influence adhesion and motility." (PMID 19898636, 2009). "In this context, CS-lipid NPs were designed to deliver anti-galectin-1 and anti-epidermal growth factor receptors-siRNAs in glioblastoma treatment because galectin-1 and EGFR are overexpressed in glioblastoma cells and are associated with the proliferation and invasion of cancer cells." (PMID 36358663, 2022). "Indeed, synergic therapeutic effects were reported by combining inhibition of galectin-1 and temozolomide to treat glioblastoma." (PMID 34572756, 2021). "Galectin-1 is involved in the resistance to radiotherapy or chemotherapy in several types of cancer including squamous cell carcinoma of the uterine cervix, hepatocellular carcinoma, glioblastoma, epithelial ovarian cancer and lung carcinoma." (PMID 34201887, 2021). "Moreover, our present findings further indicate that MCAM and LGALS1 also appear to constitute promising candidate molecules to deliver biopharmaceuticals from the blood across the BBB to glioblastomas." (PMID 32585920, 2020). "Studies have shown that Galectin-1 knockdown decreases TMZ resistance in glioblastoma." (PMID 31492191, 2019). "Vero cells, human umbilical endothelial cells (HUVECs), and microvascular endothelial cells (mVECs) all showed a 90% reduction in cell-cell fusion, and U87 glioblastoma cells showed a 60% reduction in fusion, compared to control cultures, in the presence of galectin-1." (PMID 20657665, 2010). "Galectin-1 (Gal-1), a natural galactose-binding lectin, is overexpressed in glioblastoma multiforme (GBM)." (PMID 36145722, 2022). "Polymeric chitosan NPs have also been used as an intranasal delivery system for siRNAs targeting galectin-1 expression for the treatment of glioblastoma multiforme (GBM)." (PMID 34683963, 2021). "In parallel, galectin-1 has been demonstrated to be more expressed in the invasive part of GBMs when compared to GBM core, while providing chemoresistance and pro-angiogenic singals to glioblastomas." (PMID 22583806, 2012). "Consistent with our UALCAN analysis, LGALS1, LGALS3, and LGALS9 were also overexpressed in glioblastoma." (PMID 41516291, 2025). "Our study highlights the role of LGALS1, LGALS3, and LGALS9 in glioblastoma invasion and migration via the induction of T cell apoptosis, protein homeostasis, and the maintenance of the ECM." (PMID 41516291, 2025). "We identified LGALS1, LGALS3, and LGALS9 as significantly upregulated in glioblastoma, with their overexpression correlating with adverse patient survival." (PMID 41516291, 2025). "Compared to normal brain tissues, LGALS1, LGALS3, and LGALS9 were significantly overexpressed in glioblastoma samples, with LGALS9 exhibiting the highest transcript abundance." (PMID 41516291, 2025). "Castells and colleagues reported that the expression values from only four transcripts (CHI3L1, LDHA, LGALS1, and IGFBP3) were able to distinguish two survival groups in Glioblastoma." (PMID 27121858, 2016). "Some of the new cellular targeting approaches such as galectin-1 knock-down, IL-12 administration, anti-CCR2 or anti-FGL2 might be effective and beneficial for glioblastoma therapy because these can reduce numbers of both MDSCs and GAMs." (PMID 31225500, 2019).
glioblastoma (continued). "Furthermore, there is a positive correlation between poor prognosis and increased galectin-1 amount in lesions in patients with UBUC and glioblastoma." (PMID 29671787, 2018). "Comparative immunohistochemical results showed a higher galectin-1 protein amount in invaded areas than that in non-invaded areas of human U87 and U373 xenografted glioblastoma in nude mice." (PMID 29671787, 2018).
hepatocellular carcinoma (26 papers, 2014 to 2026). A malignant tumor that arises from hepatocytes. "The high expression of Galectin-1 is associated with the migration and invasion of gastric cancer cells and poor prognosis of patients with prostate cancer and hepatocellular carcinoma." (PMID 36712844, 2022). "In this study we further reported that galectin-1 can induce autophagy to antagonize cisplatin-caused hepatoma cell death, and the enhanced antitumor effect was seen in BALB/c mice, with the cisplatin treatment in combination with TDG being associated with inhibition of soluble galectin-1." (PMID 26859293, 2016). "Interestingly, in the presence of galectin-1, cisplatin-triggered potential loss and apoptosis were both attenuated in hepatoma cells." (PMID 26859293, 2016). "The association between galectin-1 and miR-22-3p has been reported in hepatocellular carcinoma (HCC)." (PMID 39996781, 2025). "Galectin-1 (Gal1) and galectin-3 (Gal3) are reported to be overexpressed in hepatocellular carcinoma (HCC)." (PMID 38612832, 2024). "Further analysis of the relationship between galectin-1 and cisplatin-induced autophagy determined that inhibition of autophagy abolished the resistance to cisplatin conferred by galectin-1 in hepatoma cells." (PMID 35327655, 2022). "Lately, it was also demonstrated that the knockdown of LGALS1 reduces anchorage-independent growth and lung metastasis of hepatocellular carcinoma cells." (PMID 33435156, 2021). "Similar results have been observed in hepatoma cells, where galectin-1-triggered autophagy seems to help cells to resist to chemotherapy drugs by eliminating dysfunctional mitochondria." (PMID 31295873, 2019). "We therefore first tested the effect of soluble galectin-1 on chemotherapeutic agent-treated human hepatoma cells." (PMID 26859293, 2016). "In our study we found that exogenous galectin-1 is able to induce chemoresistance to cisplatin in hepatoma cells." (PMID 26859293, 2016). "We were able to determine a significant decrease in cell death of hepatoma cells after treating them with recombinant galectin-1." (PMID 26859293, 2016). "Galectin-1 is overexpressed in human hepatocellular carcinoma and is accumulated in stroma surrounding tumors." (PMID 26859293, 2016). "This protective effect of soluble galectin-1 on cisplatin-treated hepatoma cells was abolished in the presence of the galectin-1 inhibitors, lactose or thiodigalactoside (TDG), suggesting that carbohydrate-dependent interaction is responsible for this effect." (PMID 26859293, 2016). "To further determine the anti-tumor benefit of inhibiting the galectin-1 in combination with cisplatin, we used an in situ mouse hepatoma model generated by intrasplenic grafting of autologous hepatoma cells, ML-1 cells." (PMID 26859293, 2016). "Tf-LC3 transfected HepG2 cells treated with galectin-1 showed an upsurge of mRFP-LC3 punctate within 6hrs of treatment, indicating that soluble galectin-1 triggers an autophagic flux in hepatoma cells." (PMID 26859293, 2016). "In this study we have demonstrated that hepatocellular carcinoma cells were able to resist the treatment of cisplatin in the presence of soluble galectin-1." (PMID 26859293, 2016). "Galectin-1 had previously been shown to be elevated in a variety of cancers such as head and neck squamous cell carcinoma, thyroid cancer or hepatocellular carcinoma." (PMID 24708743, 2014). "In mesenchymal cells, we found an enrichment of Galectin-1 (LGALS1), which has been associated with EMT in hepatocellular carcinoma, and an increase in genes associated with the biosynthetic pathway of gangliosides, which has been previously reported for ovarian cancer." (PMID 38384845, 2024). "Up-regulating galectin-1 in the hepatoma microenvironment by soluble galectin-1 during the cisplatin treatment could facilitate the chemoresistance of cancer cells via inducing autophagy." (PMID 28842515, 2017).